PGR (progesterone receptor)
Diseases named in the same sentence as PGR in open-access papers (continued):
Sharing a sentence is not in itself a finding about the gene and the disease.
tumor (continued). "A second group of ten tumours, with high PgR concentrations and immunoreactive ER, corresponds to non ER-binding forms of receptors." (PMID 1616860, 1992). "Tumours containing 3 or 4 ER isoforms had significantly higher levels of PgR (> 90 fmol/mg protein) than those with only 1 or 2 (P < 0.001)." (PMID 1457348, 1992). "The presence of apocrine differentiation was unrelated to lymph node status, menstrual status, tumour grade or size, oestrogen receptor (E2R) or progesterone receptor status." (PMID 2202419, 1990). "Statistical examination of the results revealed no obvious correlation of gamma GT activity with histological grade of the tumour, progesterone receptor content or classification of patients by pre- or postmenopausal status." (PMID 2872909, 1986). "Tumour cytosol oestrogen and progesterone receptor status was determined in 80% of the patients with cancer, and there was a trend towards higher alpha levels in patients without receptors, but this was not statistically significant." (PMID 6161628, 1980). "Histopathological analysis demonstrated profound PDT-induced effects, including total ablation of progesterone receptor expression in the tumor matrix and a significant increase in caspase-3-mediated apoptosis in the peritumoral zone (36.3 ± 9.6 vs. 14.8 ± 2.2 cells/mm2, p<0.0001)." (PMID 41821893, 2026). "Immunostaining of the tumor showed estrogen receptor positivity (Allred score 7), progesterone receptor negativity, human epidermal growth factor receptor type 2 equivocality (fluorescence in situ hybridization (FISH) negative), and a Ki-67 labeling index of 35%." (PMID 41835700, 2026). "Clinical and tumor-related variables were analyzed, including age, menopausal status, body mass index, clinical stage, tumor grade, estrogen receptor status, progesterone receptor status, human epidermal growth factor receptor 2 status, and Ki-67 proliferation index." (PMID 42123156, 2026). "Hormonal factors, particularly progesterone receptor (PR) activation, promote tumor growth." (PMID 41439468, 2026). "We found that PTHrP is likely associated with positive progesterone receptor status, the presence of microcalcifications and lymph node invasion, but not with tumor type or grade." (PMID 41700599, 2026). "The observed early decline in Ki-67 and PgR expression provides valuable insight into tumor endocrine sensitivity and may serve as a predictive tool for monitoring therapeutic response." (PMID 40723203, 2025). "The analysis did not reveal any significant associations between high CCR7 expression and clinicopathological features, including age, tumor size, clinical stage, nodal metastasis, histological differentiation, estrogen receptor status, progesterone receptor status, or HER2/neu status." (PMID 40299690, 2025). "NAC infiltration in breast cancer is also thought to be influenced by tumor biology, with risk factors such as advanced tumor grade, positive human epidermal growth factor receptor-2 status, and negative estrogen and progesterone receptor status." (PMID 40261372, 2025). "Those with ductal cancer in situ, those whose tumour cells express the oestrogen receptor (ER) and the progesterone receptor (PgR) with a low proliferation rate as determined by the expression of Ki67 (<14%), known as Luminal A; Luminal B which expresses the ER but not the PgR and has a Ki67 (>14%)." (PMID 41373503, 2025). "The prognostic/predictive factors assessment on the tumor tissue showed positivity for estrogen (ER) and progesterone receptor (PgR) (both in 40% of the neoplastic cells), a proliferation index (Ki67) of 25% and human epidermal growth factor receptor 2 (HER2) score 1+ (negative)." (PMID 40230815, 2025). "HR+ BC is defined as a tumor expressing estrogen receptor (ER) and/or progesterone receptor (PR)." (PMID 41228290, 2025).
tumor (continued). "The majority of BML lesions express estrogen receptor (ER) and progesterone receptor (PR), suggesting that hormonal factors may play a role in tumor progression and potentially guide treatment options." (PMID 40868224, 2025). "In addition to surgical resection, management strategies typically involve adjuvant hormonal therapy targeting the tumor's estrogen and/or progesterone receptor positivity." (PMID 40978917, 2025). "Moreover, DNA methylation changes interact with MED12 mutations to form a regulatory network that modulates progesterone receptor (PR) mediated RANKL expression, promoting stem cell proliferation and tumor growth." (PMID 41463261, 2025). "Taking into account these inherent limitations, our findings suggest that risk stratification based on clinical-pathological factors, such as tumor grade, Ki67, ER, and PgR, could be useful in personalizing treatment according to patient menopausal status." (PMID 40717834, 2025). "This signature not only effectively stratifies patient risk but also delineates specific molecular pathways, such as those involving SELENOP, CDKN2A, and PGR, through which the diabetic milieu may drive tumor aggressiveness." (PMID 41244925, 2025). "Tumors of the youngest patient group displayed a higher proportion of molecular subtypes known to be associated with higher tumor aggressiveness, such as HER2-enriched and basal-like molecular subtypes, and lower ER protein and ESR1- and PGR mRNA gene expression levels, compared to older patients." (PMID 39955428, 2025). "This circRNA is associated with advanced clinical features, including larger tumor size, distant metastasis, and positive estrogen receptor (ER) and progesterone receptor (PR) status, underscoring its relevance in assessing disease progression and hormonal receptor status in BC." (PMID 40965819, 2025). "Today, the standards of BC treatment are based on determining the tumor's biological phenotype through analysis of established markers: estrogen receptor (ER), progesterone receptor (PR), human epidermal grows factor receptor 2 (HER2/neu), and marker of proliferation Kiel 67 (Ki67)." (PMID 40443562, 2025). "In addition, it recognizes benign tumors and the significance of tumor markers such as estrogen receptor, progesterone receptor, and HER2 in treatment decisions." (PMID 40228244, 2025). "Tumor size, histological grade, and biomarkers (Ki-67, PgR) were assessed pre- and post-treatment." (PMID 40723203, 2025). "Clinical and pathological characteristics, including age, tumor size, pathological type, molecular subtype, estrogen receptor (ER), progesterone receptor (PR), human epidermal growth factor receptor 2 (HER2), and proliferation cell nuclear antigen (Ki-67), were examined." (PMID 39628998, 2024). "Tumor cells were also positive for progesterone receptor (PR), desmin." (PMID 39006682, 2024). "The overall tumor was associated with focal lymphoplasmacytic infiltrate, and estrogen receptor (ER) and progesterone receptor (PR) were negative (0% nuclear stain) by immunohistochemistry (IHC)." (PMID 39069534, 2024). "A subset of these covariates could include the patient’s age, tumor size, clinical stage, ER and progesterone receptor status, and histologic subtype." (PMID 39057065, 2024). "In this study, AR expression was also correlated with various other clinicopathological prognostic factors such as age, tumor size, pT stage, nodal status, histological grade, ER expression, PgR expression, human epidermal growth factor receptor 2 (Her2) status, and molecular subtype." (PMID 39497884, 2024). "Moreover, two molecular subtypes of HGSOC, with different levels of expression of some miRNAs, including hsa-miR-16-5p, and progesterone receptor (PR) in the tumor tissue, were reported." (PMID 38255835, 2024).
tumor (continued). "The tumor cells were triple negative for estrogen receptor, progesterone receptor, and HER2/neu." (PMID 40093349, 2024). "Ki67, ER and PgR expression was assessed in all tumours pre- and post-NET treatment." (PMID 38173005, 2024). "Immunohistochemistry result for breast mass testified strongly positive staining for estrogen receptor (ER) and progesterone receptor (PR) in most tumor cells (3+), 2 + staining for human epithelial receptor 2 (HER-2), 3 + staining for androgen receptor (AR) and 10% positive Ki67 in tumor cells." (PMID 38388422, 2024). "Conversely, in consideration of clinicopathologic characteristics, we performed Kaplan–Meier survival analysis in PDAC patients bearing a tumor diameter smaller than 3 cm and showed that higher PGR expression correlated with poorer prognosis, implying the importance of PGR in tumor initiation." (PMID 38424455, 2024). "In addition to E-cadherin deficiency, ILCs exhibit a low proliferation index (Ki67), oestrogen receptor (ER) and progesterone receptor (PgR) positivity, and low tumour purity." (PMID 38600325, 2024). "In these cases, we hypothesized that progesterone receptor expression during pregnancy might have contributed to the rapid tumor growth." (PMID 39099687, 2024). "The key considerations when selecting whether to start adjuvant or neoadjuvant chemotherapy for patients with IBC-NSTs are tumour size, nodal status, nuclear grade, age, tumour subtype determined by IHC for ER, PgR, and HER2, and the Ki67 index." (PMID 38980337, 2024). "LHB and PGR exhibited high expression levels in normal samples and paratumoural regions of tumour samples; however, their expression levels were relatively low in the tumour region of tumour samples." (PMID 39548559, 2024). "The results showed a more pronounced downregulation of tumor core proliferation induced by the knockout of PGR, suggesting that PGR-induced macropinocytosis might contribute to tumor core growth in an insufficient nutrient environment." (PMID 38424455, 2024). "Furthermore, the variations in the proportion of screen-detected cancers based on tumour characteristics also exhibited significant divergence across different age groups, except in the case of ER and PgR status." (PMID 38454634, 2024). "The sampling was balanced with respect to estrogen receptor status, progesterone receptor status, human epidermal growth factor receptor status, grade, T stage, laterality, tumor volume, tumor longest dimension, and MRI resolution within the overall UAB cohort (not the overall dataset)." (PMID 39543194, 2024). "Tumour/background SUVmax was lower in progesterone receptor-positive patients (p=0.004)." (PMID 38164229, 2024). "Notably, breast cancer clinicopathological characteristics, such as patient survival time, tumor size, Ki67, pathologic stage, N stage, estrogen receptor (ER) and progesterone receptor (PR) levels, correlated well with TSP50/p-AKT/ALDH1 expression status." (PMID 39030572, 2024). "All tumours were estrogen and progesterone receptor positive." (PMID 39685707, 2024). "Elevated PGR expression acts as a tumor suppressor with a significant impact on overall survival." (PMID 38424455, 2024). "Furthermore, the results showed that the expression of LINC00944 correlated with age at diagnosis, tumour size, and estrogen and progesterone receptor expression." (PMID 36936957, 2023). "These included, for instance, lower use of core biopsy and higher reporting of tumor grade, ER/PgR expression, and HER2 amplification, pathological stage, and distance to the nearest radial margin in noninvasive cancers in general hospitals compared to oncology centers." (PMID 37504311, 2023). "Tumor size, PgR status, and MUC1 staining were independent factors relating to DFS." (PMID 37002293, 2023).
tumor (continued). "Variables associated with low pathological complete response rates were tumor grades 1-2 (OR=0.55; 95% CI=0.37-0.81; p=0.03), estrogen receptor positivity (OR=0.65; 95% CI=0.43-0.97; p=0.04), and progesterone receptor positivity (OR=0.44; 95% CI=0.29-0.65; p=0.0001)." (PMID 37871573, 2023). "Indirect validation of our approach was provided by the significant associations between high levels of progesterone receptor (PR), estrogen receptor (ER), androgen receptor (AR), GATA3 expression, and favorable tumor features as well as prolonged overall survival." (PMID 38137396, 2023). "Hormone therapy can be considered for patients with low-grade, low-volume disease who are not suitable for chemotherapy, dependent on knowledge of the hormone receptor status [estrogen receptor (ER) and progesterone receptor (PgR)] of the tumour at the time of treatment." (PMID 36696825, 2023). "An interesting finding of our study, however, is that the effect of extended aromatase inhibition on adapted disease-free survival differed between patients with tumours expressing both the oestrogen and progesterone receptor and patients with tumours expressing only one hormone receptor." (PMID 36992863, 2023). "The effect of extended aromatase inhibition on the adapted overall survival was not statistically significantly different between patients with tumours expressing both the oestrogen and progesterone receptor and patients with tumours expressing only one hormone receptor (p interaction = 0.051)." (PMID 36992863, 2023). "Functionally, we demonstrated that the silencing of SIX1, SIRT2 and CDKN2A expression could accelerate the migratory and invasive capacities of tumor cells, whereas the downregulation of PGR dramatically inhibited cancer cells migration and invasion." (PMID 37723477, 2023). "Age, race, marital status, cancer grade, tumor stage, node stage, estrogen receptor status, progesterone receptor status, human epidermal growth factor receptor--2 status, and treatment including surgery, radiation, and chemotherapy were used to establish a nomogram." (PMID 37749538, 2023). "Several factors such as tumor morphology and grade, tumor size, lymph node metastases, and expression of estrogen receptor (ER), progesterone receptor (PR) and human epidermal growth factor receptor-2 (HER-2/neu) are currently known as important parameters essential for treatment tailoring." (PMID 36380816, 2023). "Taken together, our findings suggest that ERα and PGR protein expression in CRC could be reliant on tumor sidedness alongside gender, age, and clinical stage." (PMID 37206439, 2023). "In patients with tumours expressing both the oestrogen and progesterone receptor, the 10-year adapted overall survival was 82.7% (95% CI 79.4–85.5) in the 6-year treatment group and 78.7% (95% CI 75.2–81.8) in the 3-year treatment group (HR 0.83; 95% CI 0.65–1.07)." (PMID 36992863, 2023). "The inclusion of sTIL in a prognostic model, along with tumor size, lymph node involvement, proliferation and PgR status, resulted in improved performance, which supports the independent value of sTIL as a prognostic biomarker in luminal B and high-risk tumors." (PMID 37345183, 2023). "Moreover, Girdin expression was remarkably related to tumor volume, advanced cancer, estrogen and progesterone receptor expression, and lymph node metastasis (LNM)." (PMID 36604355, 2023).
tumor (continued). "Next, we examined the differences in clinicopathological characteristics such as tumor size, grade, lymph node status, lymphovascular invasion, the density of tumor-infiltrating lymphocytes, estrogen receptor, progesterone receptor, and HER2 status between the parous and nulliparous groups." (PMID 37160509, 2023). "Treatments that target hormone receptors are an attractive option, as studies have shown that ~70% of LGSOCs are positive for estrogen receptor (ER) and ~30% are positive for progesterone receptor (PR), defined as weak (1% to 50% of tumor cell nuclei) or strong (≥50%)." (PMID 38239650, 2023). "In malignant tissues, the proteins of ERα and AR increased significantly and concurred with decreases in ERβ and PGR, and the tumor clinical characteristics correlated positively with ERα and AR, whilst negatively with ERβ and PGR, supporting the contributions of receptors to colon carcinogenesis." (PMID 37206439, 2023). "However, researchers studying subtypes usually focus on estrogen and progesterone receptor status to establish tumor subtype; it is also relatively usual to combine pre- and post-menopausal women." (PMID 38034128, 2023). "Furthermore, most tumor cells were estrogen receptor (ER)- and progesterone receptor (PgR)-positive." (PMID 36765343, 2023). "To specifically determine the contribution of sTIL to the prognostic performance of a multivariable Cox regression model for RFI in luminal B tumors, we built a nested model adding sTIL to a baseline model including tumor size, number of positive nodes, PgR status and Ki67." (PMID 37345183, 2023). "The tumor organoids were successfully established, which was demonstrated by morphology and immunohistochemistry staining (estrogen receptor [ER], progesterone receptor [PR], and human epidermal growth factor receptor‐2 [HER2]) compared to the primary pathological patterns." (PMID 38053815, 2023). "All cases were confirmed to be ER+, while eight patients had an ER+/PgR− tumor." (PMID 36428975, 2022). "Traditionally, breast cancers are classified according to histology, tumor size, lymph node status, histological grade, and the biomarkers ER (estrogen receptor), PR (progesterone receptor), and human epidermal growth factor receptor 2 (HER2) status, which are universally recommended." (PMID 36077734, 2022). "The authors demonstrated that characteristics such as negative progesterone receptor status, and tumor size ≥ 4 cm were related to an increased risk of developing LRR." (PMID 35623619, 2022). "Currently, BC classification and therapy assessment are mainly based on tumor staging/grading and the following molecular biomarkers: estrogen receptor (ER), progesterone receptor (PgR), human epidermal growth factor receptor 2 (HER2) and Ki-67 (proliferation marker)." (PMID 35565446, 2022). "Moreover, this tumour model lacks expression of the oestrogen and progesterone receptor and overexpresses EbrB2 and cyclin D1 as the tumour progresses, which mimics human breast cancers with poor prognosis." (PMID 35808806, 2022). "The tumor cells are usually ER and progesterone receptor (PR) positive and lack HER2 amplification." (PMID 34734332, 2022). "In 204 breast cancer patients, NEDD9 expression was significantly correlated with tumor grade (χ2 = 4.311, P = 0.038), ER (estrogen receptor) (χ2 = 11.16, P = 0.001), PR (progesterone receptor) (χ2 = 4.026, P = 0.045), Ki67 (χ2 = 6.558, P = 0.01) and lymphatic metastasis (χ2 = 14.79, P = 0.0001)." (PMID 35549691, 2022). "Tumor biological factors such as negative estrogen and progesterone receptor status were associated with positive margins, whereas the grade of differentiation was not." (PMID 35625972, 2022). "While these data suggest that cut-points for relative expression higher and lower than 10 might be appropriate for PgR − and PgR + tumours, respectively, the number of cases available to address this within the subgroups was too small to provide confidence." (PMID 36096872, 2022).